INS (insulin)
Diseases named in the same sentence as INS in open-access papers (continued):
Sharing a sentence is not in itself a finding about the gene and the disease.
Obesity (continued). "This is particularly relevant if one considers that in diet-induced obesity, insulin resistance develops in all muscles, despite their variability in fiber type distribution." (PMID 34580412, 2021). "The interaction of adiponectin with leptin, insulin and estrogen is also discussed, which provides a promising therapeutic target for the treatment of obesity related tumors." (PMID 34485124, 2021). "Obesity plays a key role in developing abnormalities in sex hormone metabolism and insulin levels, because of the excessive accumulation of adipose tissue or body fat." (PMID 34530776, 2021). "The adipose-specific knockout of mTORC2 suppresses insulin-stimulated glucose uptake and prevents development of obesity." (PMID 34956089, 2021). "During states of pancreatic inflammation, TRPV1 activation increases expression of calcitonin gene-related peptide, known to disrupt insulin release from pancreatic β-cells, promoting IR and obesity." (PMID 34673019, 2021). "Accordingly, this review will focus on the molecular basis of the preventive activity of flavonoids related to insulin signaling in T2D and obesity." (PMID 34208379, 2021). "While seven of the 14 significant SNPs belong to obesity genes, four from insulin signaling pathway, two from reproductive pathway genes and one plays a role in peptide hormone metabolism." (PMID 34784930, 2021). "In mice, fecal transplantation from an obese to a lean animal induces weight gain and obesity, while in humans, the transplanting of lean fecal microbiota into an obese individual improves insulin sensitivity and microbial diversity." (PMID 34769060, 2021). "The aim of our experiment was to evaluate the influence of chronic antioxidants administration on myocardial sphingolipid state and intracellular insulin signaling as a potential therapeutic strategy for obesity-related cardiovascular IR." (PMID 34684414, 2021). "Obese youth, as a group, showed statistically greater levels of unmethylated CHTOP and both unmethylated and methylated INS compared to lean control youth—findings suggestive of β-cell death in youth with obesity." (PMID 33670079, 2021). "Between 44% and 70% of women with PCOS are insulin-resistant, and women with PCOS and obesity are more insulin-resistant than obese controls." (PMID 34071499, 2021). "GW501516 increase FA oxidation in the skeletal muscle, reduce fat gain in HFD fed mice, and promote increased glucose tolerance and insulin sensitivity in the ob/ob mouse model of obesity and IR." (PMID 33926085, 2021). "Cluster 3, including 25% of patients, was labeled as mild obesity-related diabetes (MOD) characterized by obesity, low age, average β-cell function, and insulin resistance." (PMID 34276555, 2021). "The overweight individuals were further classified as insulin sensitive with overweight or obesity (ISO, HOMA-IR<2.5) or insulin resistant with overweight or obesity (IRO, HOMA-IR≥2.5) (n=30 each)." (PMID 35046901, 2021). "Rats not expressing Sfrp5 show proliferation of pancreatic β-cells via IGFBP-3, an insulin-compensatory lesion observed in obesity." (PMID 34371968, 2021). "These solid results indicate that MCA has promising bioactivity in regulating diet-induced obesity, insulin sensitivity, hyperlipidemia and hepatic steatosis by supporting healthy populations or abundances of inferred important bacteria." (PMID 33808007, 2021). "The general opinion states, however, that DHEA should evoke insulin sensitization and counteract obesity through downregulation of 11β-hydroxysteroid dehydrogenase type 1 (11β-HSD1)." (PMID 34069293, 2021). "In this review article, we summarize and interpret studies examining the role of ATX, LPA receptors, and LPP3 in energy homeostasis and insulin function with an emphasis on diet-induced obesity." (PMID 34502491, 2021).
Obesity (continued). "miR-34a was increased in type 2 DM patients who were overweight and obese, and miR-34a was differentially affected by glycemia, obesity, insulin treatment, and the presence of nephropathy and diabetic foot." (PMID 33799467, 2021). "Neuron-specific inactivation of P2Y6R reduces food intake and improves systemic insulin sensitivity in obesity." (PMID 34943862, 2021). "Subsequently, our objective was to investigate the effects of obesity and physical exercise on obese animals stimulated with insulin." (PMID 34203825, 2021). "Secondly, other studies in murine models reported that cromolyn, a mast cell stabilizer, reduces obesity and adipose tissue fibrosis, while it promotes insulin sensitivity." (PMID 34093556, 2021). "Whereas mice with knockdown of CGI-58 showed hepatic steatosis as well as increased DAG content, they remained insulin sensitive and were protected from diet-induced obesity and glucose intolerance." (PMID 33923817, 2021). "This is essentially based on the high demand on β-cells to increase insulin secretion in obesity, leading eventually to β-cell death or dysfunction." (PMID 33672162, 2021). "In terms of metabolic aspect, insulin sensitivity is considered one of the hallmarks of NAFLD, is strongly associated with obesity." (PMID 34307250, 2021). "In vivo, we demonstrate that LMO3 preserves a metabolically beneficial visceral adipose tissue expansion and insulin sensitivity along with enhanced adiponectin secretion during obesity." (PMID 34018016, 2021). "As expected, the obesity + DM group presented higher fasting glycemia, insulin levels and glycated hemoglobin (HbA1c) levels when compared to every other group." (PMID 34769201, 2021). "Asiatic acid has shown anti-diabetic and anti-obesity activities by enhancing insulin secretion and reducing the production of fatty acids in adipose tissue, respectively." (PMID 34885816, 2021). "The study was designed to analyze the possible role of Stevioside, a characteristic sugar from leaves of Stevia rebaudiana (Bertoni) on insulin signaling molecules in gastrocnemius muscle of obesity and hyperglycemia-induced T2DM rats." (PMID 34946771, 2021). "Third, many studies have shown that the polymorphism in LEPR is associated with the levels of blood glucose, insulin, leptin, and triglyceride, and LEPR deficiency can directly lead to the accumulation of fat, resulting in obesity." (PMID 34419151, 2021). "It is known that resistin suppresses the ability of insulin to stimulate cellular glucose uptake, playing a role in obesity, insulin resistance and diabetes." (PMID 34199040, 2021). "The focus of this review is to summarize the impact of transmembrane receptor protein tyrosine phosphatase (RPTPs) in the insulin signaling cascade and secretion, and their implication in metabolic diseases such as obesity and T2DM." (PMID 34071721, 2021). "Another study has made use of Golden Syrian hamsters that were fed a pro-obesity diet consisting of an excess of nine types of palatable industrially processed foods; highly fatty, sugary and salty, to induce obesity, insulin resistance and oxidative stress." (PMID 33805942, 2021). "Different reports have described that FGF15 acts in the brain of rodent models of obesity and enhances insulin sensitivity, improves glucose tolerance, decreases food intake and body weight, and increases energy expenditure." (PMID 34260412, 2021). "We demonstrate that patients with IIH have dysregulated systemic metabolism, in excess of that mediated by obesity, being more insulin resistant in the context of hyperleptinemia and adipocyte leptin hypersecretion." (PMID 33848268, 2021). "Obesity-induced dyslipidemia has been identified as “metabolic-related dyslipidemia”, which is mainly driven by the effects of insulin resistance and proinflammatory adipokines." (PMID 35010598, 2021). "NPY is elevated in obesity and promotes energy storage, and decreases in response to administration of leptin or insulin." (PMID 33716966, 2021).
Obesity (continued). "Specifically, increased levels of glucose and insulin, reflecting IR, which interacts with obesity, promoted colorectal epithelial proliferation; the elevated insulin levels stimulated the growth of CRC in both cell lines and an animal model." (PMID 34692549, 2021). "Both obesity phenotypes are characterized by a significant increase in their fasting insulin and HOMA-IR compared to lean patients." (PMID 34684461, 2021). "Further studies are needed, especially in humans, to unravel the role of these natural compounds on insulin signaling during obesity." (PMID 34208379, 2021). "Our studies using exogenous insulin to induce hyperinsulinemia in vivo demonstrate that insulin promotes breast cancer growth in the context of obesity." (PMID 33495474, 2021). "Visfatin is another proinflammatory adipokine that plays a role in insulin sensitivity and whose production is increased in obesity and correlates with visceral adiposity." (PMID 34884217, 2021). "PPARɣ and PGC1α play key roles in adipogenesis and insulin sensitization, and reportedly increase in expression during obesity." (PMID 34103691, 2021). "The obesity-related changes include a chronic state of low-grade inflammation, adipokine imbalances, elevated levels of growth factors, and hormones, such as insulin, insulin-like growth factor (IGF)-1, and estrogens." (PMID 34631264, 2021). "Several mechanisms were proposed to be involved in ATX upregulation in the context of diet-induced obesity and metabolic disease, including inflammation, high glucose, and insulin." (PMID 34502491, 2021). "The VN plays an important role in glucose homeostasis, in particular, by modulating insulin secretion by the pancreas, a response altered in obesity." (PMID 34248663, 2021). "In the lean group, < 1.0% of mothers were treated with insulin during pregnancy while in the obesity group, 2.40% of mothers were treated with insulin." (PMID 33743677, 2021). "The primary finding of our study was that Drp1 inhibition in vivo using the pharmacological inhibitor Mdivi‐1 attenuated skeletal muscle insulin resistance at the early stage in the development of diet‐induced obesity." (PMID 33904649, 2021). "When individuals with obesity consumed genistein capsules (50 mg/day) for two months, their intestinal flora was altered, insulin resistance was improved, and skeletal muscle fatty acid oxidation was promoted." (PMID 34641407, 2021). "It has been reported that exosomes from adipose MSCs ameliorated HFD-induced obesity in mice through anti-inflammation, improving insulin sensitivity and decreasing hepatic steatosis." (PMID 34174964, 2021). "With obesity, and even with advanced aging, glucose homeostasis becomes perturbed, as tissues become insulin insensitive leading to less glucose uptake and more endogenous glucose production." (PMID 33917279, 2021). "GPR41- and GPR43-KO mice exhibit reduced GPL-1 levels, consistent with their propensity for obesity and impaired insulin sensitivity." (PMID 34684670, 2021). "Inactivation of orexin receptor type 1 in serotonin transporter-expressing cells of mice reduced insulin sensitivity in diet-induced obesity, mainly by decreasing glucose utilization in brown adipose tissue and skeletal muscle." (PMID 34475397, 2021). "The role that HIF activation plays in the context of obesity associated disease is complicated by evidence of a link between HIF and insulin signalling." (PMID 34692739, 2021). "Pathways negatively related to obesity included adipocytokine signaling, insulin signaling, and fatty acid metabolism, which reflect a dysregulation of adipokines and insulin signaling in obese patients." (PMID 34093637, 2021). "Insulin is an anabolic, fat-storage hormone, and hyperinsulinemia results in varying degrees of obesity depending on the fat storage capacity of the individual (the “personal fat threshold”)." (PMID 34557366, 2021).
Obesity (continued). "VS extract effectively elicited anti-obesity activity with a significant decrease in plasma glucose, insulin, HOMA-IR, and TG levels." (PMID 33671428, 2021). "It was also observed that subjects with obesity are more prone to suffer from gingivitis, which is most likely due to increased insulin resistance." (PMID 33767669, 2021). "In contrast, however, subcutaneous NMU administration improves glucose tolerance by increasing insulin secretion in mice with diet-induced obesity." (PMID 33921859, 2021). "GNAI2 is known to serve as a crucial regulator of diet-induced obesity, which improves insulin sensitivity." (PMID 34269146, 2021). "Here, we demonstrate that myeloid lineage–specific ANT2 depletion improved insulin sensitivity and glucose tolerance in obesity." (PMID 34676827, 2021). "In summary, we found that the expression of NOX5 in the endothelium under obesity conditions is able to induce an upregulation of important insulin signalling intermediaries, such as Ir-B, Cav1, and Glut4 in the neighbouring adipose cells." (PMID 33800461, 2021). "We also demonstrated in our diet-induced obesity mouse model that neutralising ADAM19 therapy results in weight loss and improves insulin sensitivity." (PMID 33904577, 2021). "Obesity will increase aromatization of estrogen in adipose tissue, which in turn modulates sensitivity to insulin." (PMID 33482868, 2021). "Long chain omega-3 polyunsaturated fatty acids (ω-3PUFA) supplementation in animal models of diet-induced obesity has consistently shown to improve insulin sensitivity." (PMID 33753887, 2021). "All known factors affecting insulin sensitivity—including obesity and other environmental factors such as poor diet, physical inactivity, alcohol, and stress—explain less than one-third of the variation in insulin sensitivity in the population." (PMID 34639470, 2021). "Obesity is the strongest risk factor for GDM and women who are overweight and obese have decreased insulin sensitivity compared to lean women." (PMID 34416903, 2021). "Several studies have shown that retinoids induce the secretion and sensitivity of insulin and gluconeogenesis, resulting in a reduction in the incidence of early obesity." (PMID 34977070, 2021). "Despite severe obesity aged female mice exhibited normal insulin responsiveness, and mild glucose dysmetabolism and hepatocellular damage." (PMID 34099626, 2021). "Insulin sensitivity, early obesity, and PPARγ expression were assessed in CD24 knockout (KO) mice and compared to wild-type (WT) mice." (PMID 33467499, 2021). "It has been reported that adipose MSC-derived exosomes ameliorated HFD-induced obesity in mice through inhibiting inflammation, improving insulin sensitivity, and decreasing hepatic steatosis." (PMID 34174964, 2021). "The metabolites produced by bacteria such as short chain fatty acids (SCFAs) can regulate appetite, insulin signaling, and adipogenesis; therefore, the intestinal microbiota can direct its host to storage lipids in adipose tissue, leading to obesity." (PMID 34681728, 2021). "At an equivalent BMI, higher insulin sensitivity was observed in PWS subjects compared to subjects with common obesity." (PMID 34830599, 2021). "Firmicutes, specifically belonging to the Ruminococcaceae family, were positively correlated with subcutaneous adipose tissue, plasma acetate, and insulin sensitivity in brown adipocytes, inferring their relevance in obesity and MetS." (PMID 34491882, 2021). "GPAM knockout mice have reduced adiposity and its inhibition reduces food intake and increases insulin sensitivity in diet-induced obesity." (PMID 34128465, 2021). "Low-grade inflammation is known to be involved in the pathogenesis of obesity-related metabolic syndrome, insulin secretion defects, and impaired energy homeostasis." (PMID 34975748, 2021).
Obesity (continued). "In cases of T2DM or obesity, where chronic insulin elevation leads to increased lipid synthesis and a lipid-rich environment, one would expect the SARS-CoV to more readily form replication organelles and increase virus production." (PMID 33440724, 2021). "In mouse obesity models, IL-33 plays a protective role by reducing obesity and increasing glucose and insulin tolerance." (PMID 33608010, 2021). "Although previous studies have reported that inulin addition was related to improve metabolic disorders in human and rodents, so many controversial reports made some confusions in its anti‐obesity and insulin sensitivity." (PMID 34262707, 2021). "MOTS-c levels are inversely correlated with markers of insulin resistance and obesity including BMI, waist circumference, waist-to-hip ratio, fasting insulin level, HOMA-IR, HbA1c." (PMID 33468709, 2021). "The aim of the present review is summarizing the molecular basis of the chemopreventive activity of flavonoids related to insulin signaling during T2D and obesity." (PMID 34208379, 2021). "Vascular endothelial growth factor (VEGF) signaling pathway: A report shows that inactivation of VEGF enhances the insulin sensitivity in high-fat-diet mice, which is an efficient approach to ameliorate obesity." (PMID 34889899, 2021). "We defined MetS using five criteria: impaired insulin metabolism and glucose tolerance, obesity in the abdominal area, dyslipidemia, and hypertension." (PMID 34819073, 2021). "In contrast, irisin levels appear to be higher in dysmetabolic states, such as obesity, possibly reflecting a condition of irisin resistance or a compensatory increase for the metabolic abnormalities and insulin resistance characteristic of these patients." (PMID 33671882, 2021). "This review summarizes and interprets current literature on the role of the ATX-LPA-LPP3 axis in the regulation of energy homeostasis, insulin function, and adiposity at baseline and under conditions of obesity." (PMID 34502491, 2021). "Several factors can influence insulin sensitivity such as obesity and fat distribution, age and sex, genetics, exercise, dietary nutrients, and hormones (glucagon, epinephrine, cortisol, leptin, growth hormones, sex hormones, amylin)." (PMID 33467677, 2021). "INPP4B expression protects the liver from steatosis, mediates insulin sensitivity, and links obesity to neoplastic changes in the prostate epithelium." (PMID 33772116, 2021). "In a multi-center study (n=2495), we used unsupervised machine learning to cluster patients with obesity from Shanghai Tenth People’s hospital (n=882, main cohort) based on three clinical variables (AUCs of glucose and of insulin during OGTT, and uric acid)." (PMID 34335479, 2021). "Animal studies have shown that the transportation of insulin from blood flow to the CNS can be influenced by many factors related to obesity and T2D." (PMID 33917464, 2021). "Leptin levels with notable sexual dimorphisms changes significantly in early obesity and was observed to also correlate with insulin levels." (PMID 34439950, 2021). "study has indicated the anti-obesity results of Nigella, due to its affirmative effects against insulin sensitivity and its immune-modular effects." (PMID 33842824, 2021). "TCPTP deficiency in POMC neurons can enhance insulin-induced AKT phosphorylation, improve glucose homeostasis, and prevent diet-induced obesity by increasing white adipose tissue browning and energy expenditure." (PMID 34268308, 2021). "Obesity and impaired maternal glucose metabolism are strongly associated with gestational diabetes mellitus (GDM), macrosomia, and infant insulin resistance." (PMID 35010978, 2021). "PN50ME significantly suppressed dyslipidemia, steatosis and hepatocyte ballooning, insulin resistance, oxidative stress, hepatocyte injury, inflammation, and obesity in a rat model of HFD-induced NAFLD." (PMID 34441028, 2021).